GATA4 (GATA binding protein 4)
Diseases named in the same sentence as GATA4 in open-access papers (continued):
Sharing a sentence is not in itself a finding about the gene and the disease.
cardiac hypertrophy (continued). "Dephosphorylated NFAT-3 is transferred to the nucleus to further interact with GATA-4 transcription factors to form complexes that participate in the development of myocardial hypertrophy." (PMID 37251311, 2023). "In cardiopathy, circRNA_000203 aggravates cardiac hypertrophy by suppressing miR-26b-5p and miR-140-3p, leading to enhanced GATA-binding protein 4 (Gata4) levels." (PMID 36890830, 2023). "We have previously shown that NEU1 translocated to the nucleus to bind with transcriptional factors GATA4, promoting cardiac hypertrophy and remodeling." (PMID 36973294, 2023). "Whereas, in mice that have undergone TAC surgery or ISO injection, this reduction coincided with resistance to cardiac hypertrophy, recapitulating phenotypes in Gata4 conditional knockout mice." (PMID 37789015, 2023). "For instance, inhibition of KCNQ1OT1 by hsa-miR-140-3P exacerbates ischemia–reperfusion injury, and hsa-miR-140-3p inhibits cardiac hypertrophy through targeting Gata4." (PMID 37626628, 2023). "The authors proposed a mechanism that consists of GATA4 direct binding to NPPA-AS1 as a scaffold for EP300 recruitment, promoting subsequent GATA4 acetylation and pathological cardiac hypertrophy." (PMID 37569677, 2023). "Apart from its role in cardiac morphogenesis at the embryonic stage, GATA-4 is crucial for cardiac hypertrophy by regulating transcriptional activation of cardiac-specific genes." (PMID 37372403, 2023). "It was reported that circRNA_000203 suppressed miR-26b-5p/miR-140-3p to abolish the inhibition of Gata4, which aggravates cardiac hypertrophy." (PMID 35306484, 2022). "There is evidence that GATA4 is related to myocardial hypertrophy, and overexpression of GATA4 induces myocardial hypertrophy in experimental models." (PMID 36177479, 2022). "CircRNA_000203 aggravates cardiac hypertrophy by inhibiting the binding of miR-26b-5p and miR-140-3p to Gata4." (PMID 36434693, 2022). "The activation of the GATA-binding factor 4 (GATA4) transcription factor induces cardiac hypertrophy and heart failure." (PMID 35173540, 2022). "In adult hearts, transgenic mice with cardiomyocytes-specific overexpression of GATA4 by 2.5-fold displayed cardiac hypertrophy." (PMID 35185581, 2022). "CircRNA_000203 has aggravated the development of cardiac hypertrophy through elevating the level of Gata4 via inhibiting miR-26b-5p and miR-140-3p." (PMID 35251305, 2022). "Deacetylation of GATA4 by Sirtuin 7 significantly ameliorates transverse aortic constriction (TAC)-induced cardiac hypertrophy in mice." (PMID 35185581, 2022). "Recently, it has also been found that deacetylation of GATA4 has an anti-myocardial hypertrophy effect." (PMID 36177479, 2022). "After supplementing with metformin or rapamycin, autophagic flux and GATA4‐dependent myocardial hypertrophy, aging and inflammation were partially rescued." (PMID 35390228, 2022). "For example, miR-140-3p is adsorbed by circRNA_000203, leading to enhanced Gata4 levels and thus exacerbating cardiac hypertrophy." (PMID 35681442, 2022). "In previous studies, IL-18 was found to act via PI3K/PDK1/Akt/GATA4-induced cardiac hypertrophy and play an important role in cardiac remodeling and heart failure." (PMID 37551283, 2022). "Overexpressed in the heart of neonatal mice compared to adults and upregulated during cardiac hypertrophy, GATA4 was identified as a key mediator of hypertrophy." (PMID 34208388, 2021). "Collectively, these results indicate that acetyltransferase p300-induced acetylation of transcription factors including GATA4 plays a pivotal role in PE-induced cardiac hypertrophy and heart failure." (PMID 34831061, 2021). "Since GATA4 plays a significant role in mammalian cardiac development and serves as a mediator of cardiac hypertrophy and acts as an important regulator of calcium signaling, we studied the expression of GATA4 in diabetes-associated cardiac pathology." (PMID 34885867, 2021).
cardiac hypertrophy (continued). "Regarding the effect on cardiac hypertrophy, both miR-23a, miR-140, and miR-146a mediate cardiac hypertrophy through targeting the ubiquitin-proteasome pathway, GATA binding protein 4 and dihydrolipoyl succinyltransferase, respectively." (PMID 34646160, 2021). "Conditional knockout of Gata4 leads to the loss of regenerative ability in neonatal mice, and overexpression of Fgf16 via AAV9 in the Gata4-deficient heart partially rescues cardiac hypertrophy and improves heart function after injury." (PMID 33821373, 2021). "ERK1/2 is an important member of the MAPK family, and its phosphorylation can lead to interaction with GATA4 and myocardial hypertrophy." (PMID 34690749, 2021). "For instance, expression of Gata4 in the heart, a transcription factor required for cardiac hypertrophy, was found to be inhibited by miR-208a." (PMID 34957257, 2021). "First, ERK phosphorylation is typically induced, not suppressed by cardiac stress/damage and is required for changes in the expression of cardiac hypertrophy genes regulated by the GATA4 transcription factor." (PMID 33949649, 2021). "In ANP+/–(KO) offspring, the significantly elevated levels of acetyltransferase p300 and acetylated GATA4/GATA6 contribute to gestational hypertension-induced cardiac hypertrophy." (PMID 34831061, 2021). "CircRNA_000203 promoted cardiac hypertrophy by inhibiting miR-26b-5p and miR-140-3p to enhance the Gata4 level." (PMID 34174955, 2021). "GATA-4 is a transcription factor that promotes cardiac hypertrophy by translocating to the nucleus and activating hypertrophic gene expression." (PMID 32566092, 2020). "A previous study has reported that MITF transcriptionally promotes GATA4 expression by binding to the E box in the GATA4 promoter in cardiac hypertrophy, responding to stress from ischemia." (PMID 32104183, 2020). "Following DOX administration, the activation of transcription factor GATA-4 involved in expression of cardiac hypertrophy was investigated." (PMID 33374365, 2020). "The transcription factor GATA-4 acts as a downstream part of the activated calcineurin signaling pathway, plays an important role in cardiac adaptive responses including cardiac hypertrophy and survival." (PMID 33374365, 2020). "It is well established that GATA4 plays an important role in cardiac hypertrophy, acting as a rescue agent." (PMID 33114386, 2020). "Calcineurin activation hasa regulatory role during cardiac hypertrophy through NFATc3/GATA4 pathway." (PMID 31211784, 2019). "The downstream transcription factor GATA4 is a nuclear transcription factor closely related to cardiac development and plays a key role in the development of cardiomyocyte differentiation, cardiac hypertrophy, and HF." (PMID 32454845, 2019). "Since MEF2c is connected to GATA4 and Isl-1, other groups have documented the upregulation in gene expression in connection with cardiac hypertrophy." (PMID 31717562, 2019). "Angiotensin II is part of the renin–angiotensin system and has also been used to stimulate cardiac hypertrophy in cardiomyocytes in vitro by mediating hypertrophic growth via binding of GATA4." (PMID 31717562, 2019). "For example, HEY2 expression levels influence cardiac hypertrophy and the progression to heart failure in response to pressure overload through modulation of apoptosis and GATA4 activity." (PMID 30816197, 2019). "KLF15 represses cardiac hypertrophy in part through the modulation of the activity of GATA4 and MEF2, which are central mediators of hypertrophic remodelling acting through ANP and BNP." (PMID 29970016, 2018). "In conclusion, gentisic acid effectively inhibited cardiac hypertrophy and fibrosis in a mouse model of pressure overload through downregulation of Sp1/GATA4 expression and ERK1/2 signalling pathways." (PMID 30256522, 2018). "Our results showed that gentisic acid treatment did indeed attenuate cardiac hypertrophy and fibrosis, through down‐regulation of Sp1/GATA4 and MAPK signalling." (PMID 30256522, 2018).
cardiac hypertrophy (continued). "In the present study, we determined the expression of CaMKII, CaN, and GATA-4 and the nuclear translocation of NFAT-3, all of which are implicated in the development of cardiac hypertrophy and apoptosis and are mediated by [Ca2+]i." (PMID 30364197, 2018). "Another hypertrophic mediator, p38 MAPK, was found to mediate concentric cardiac hypertrophy by phosphorylated GATA4 to further expressed hypertrophic response genes such as ANP and BNP." (PMID 28479925, 2017). "When hypertrophy of the heart is induced by pressure overload, only 49 % of the GATA4 bound regions are found shared between ascending aortic band and the sham condition." (PMID 27497925, 2017). "In the adult mouse heart, GATA4 plays a major role to promote cardiac hypertrophy and cardiac angiogenesis and to maintain cardiac function during pathological pressure overload, which also leads to increased cardiac GATA4 protein abundance." (PMID 28053183, 2017). "Experiments in transgenic mice showed that activated T cells were generated by nuclear factor of activated T lymphocyte (NFAT-3) and the GATA4, two specific transcription factors that play important roles in cardiac hypertrophy." (PMID 28335423, 2017). "GATA4 binding is not only changed dynamically between embryonic development and the adult heart, but also in the pathological state of cardiac hypertrophy, a condition in which GATA4 is well known to play a role." (PMID 27497925, 2017). "Previous studies indicate that ERK1/2 and JNK1/2 phosphorylate various substrates such as transcription factors GATA4 and NFATs, subsequently triggering the transcription of hypertrophy-related genes, and eventually result in cardiac hypertrophy." (PMID 28479925, 2017). "The inhibitory effect of pyridostigmine on the CaN/NFAT3/GATA4 signalling pathway plays important roles in cardiac hypertrophy." (PMID 28296184, 2017). "GATA4 plays a key role in regulating cardiac hypertrophy and HF by binding to the promoters of BNP, ANF, alpha-MHC, and beta-MHC genes, and thus, controls their expressions in the heart." (PMID 27893819, 2016). "GATA4, which is a zinc finger transcription factor, plays a pivotal role in cardiac development and cardiac hypertrophy." (PMID 26973524, 2016). "When the activated MEK1 transgenic mice were crossed to the GATA4 S105A mutant mice cardiac hypertrophy was significantly blunted, suggesting that phosphorylation of GATA4 at Serine 105 is required for MEK-ERK1/2 hypetrophic function." (PMID 26257652, 2015). "GATA-4 has been shown to have an important role in cardiac proliferation, differentiation and survival as well as the cardiac hypertrophy process." (PMID 25975979, 2015). "Taken the central role of GATA4 in cardiac hypertrophy and growth, more data are warranted to clarify the role of GATA4 as a downstream target of CaMKII." (PMID 24659967, 2014). "Gata4 is a key transcription factor which is involved in the heart development and cardiac hypertrophy." (PMID 25101666, 2014). "To elaborate on the DNA methylation array results, we selected several DMRs at different gene loci related to cardiac hypertrophy including Mef2c, Tnnt2, Myh6, Myh7, and Gata4 and body weight Ins2 for bisulfite sequencing." (PMID 24475304, 2014). "A large body of evidence suggests that GATA4 is an important regulator of cardiac genes involved in pressure overload-induced cardiac hypertrophy, including the hypertrophic agent ANP." (PMID 24885948, 2014). "The transcriptional code that programs cardiac hypertrophy involves the zinc finger-containing DNA binding factors GATA-4 and GATA-6, both of which are required to mount a hypertrophic response of the adult heart." (PMID 24391969, 2013). "Other genes of note that were regulated by NRG-1β treatment in this and prior studies include hopx (homeodomain only protein x), a suppressor of serum response factor and GATA4, that regulates myocyte differentiation and cardiac hypertrophy." (PMID 23437060, 2013).
cardiac hypertrophy (continued). "Accordingly, a recent publication was able to demonstrate that PLZF can increase GATA-4 gene expression downstream of angotensin II in the context of cardiac hypertrophy." (PMID 23469216, 2013). "GATA-4 a cardiac restricted zinc finger transcription factor has been shown to control several genes up regulated during cardiac hypertrophy including β-MHC, cardiac troponin-C, atrial natriuretic factor, sodium/calcium exchanger (NCX), A1-R." (PMID 22792196, 2012). "In cardiac tissues, the hyperglycemia-induced ROS activate the MEK/ERK pathway to increase GATA-4 phosphorylation, which in turn generates cardiac hypertrophy." (PMID 22248260, 2012). "Previous studies have shown that KLF15 inhibits cardiac hypertrophy by repressing the activity of pivotal cardiac transcription factors such as GATA4, MEF2 and myocardin." (PMID 22586493, 2012). "The AT2 initiated GATA4 activation and cardiac hypertrophy are novel and somewhat surprising in view of the generally recognized AT2 function directed to growth inhibition." (PMID 22558183, 2012). "GATA-4 has been shown to control several genes up-regulated during cardiac hypertrophy including β-MHC and ANF." (PMID 22792196, 2012). "This critical role of GATA4 is supported by the recent observations that GATA4-deleted mice lose the ability for cardiac hypertrophy following pressure overload and exercise stimulation, and overexpression of GATA4 induces cardiac hypertrophy." (PMID 22474596, 2012). "In the present study, we identified signals for hyperglycemia-induced cardiac hypertrophy, especially for GATA-4 accumulation in the nucleus, increasing cTnI over-expression." (PMID 21702924, 2011). "However, at 8 weeks post-TAC, a significant increase in heart weight was exclusively observed in the homozygous ΔuORF mice, highlighting the crucial role of GATA4 uORF in limiting cardiac hypertrophy." (PMID 40463063, 2025). "The expression of Brg1 in both TAC and isoprenaline-induced cardiac hypertrophy models was upregulated, demonstrating that hypertrophy signaling promotes the enrichment of Brg1 to regulate the transcriptional activator of the pro-hypertrophy gene, GATA4, and promote cardiac hypertrophy." (PMID 38584203, 2024). "In addition to NFAT-3, GATA-4 is a transcription factor that plays an important role in the downstream part of the activated calcineurin signaling pathway, mediating the cardiac hypertrophy response." (PMID 39408900, 2024). "Blocking GATA4 autophagic degradation promoted cardiac hypertrophy." (PMID 39931517, 2024). "Finally, in myocardial diseases, the IDO1-KYN-AhR pathway exacerbates pathological myocardial hypertrophy by modulating GATA4." (PMID 38883986, 2024). "Therefore, the calcineurin/NFAT/GATA4 pathway functions as an essential effector during cardiac hypertrophy formation." (PMID 39408900, 2024). "Through a series of in vivo and in vitro experiments, they demonstrated that knockout of IDO1 and down-regulating KYN could mitigate pathological myocardial hypertrophy by modulating the expression of GATA4 (GATA binding protein 4) via AhR regulation." (PMID 38883986, 2024). "GATA4 is a transcription factor that regulates cardiac hypertrophy and survival." (PMID 39931517, 2024). "However, the relationship between ER stress and GATA4 hasn't been explained well in pathological cardiac hypertrophy." (PMID 37219631, 2023). "Notably, increased GATA4 protein activity is essential for inducing cardiac hypertrophy during pressure overload in mouse and rat models." (PMID 37789015, 2023). "Similarly, Sirt7 modulates the transcriptional activity of GATA4 by deacetylating GATA4 and ameliorates phenylephrine-induced cardiac hypertrophy." (PMID 37175583, 2023). "Moreover, p-Akt upregulated CITED4 to promote myocardial hypertrophy by promoting the expression of GATA4." (PMID 36834623, 2023).
cardiac hypertrophy (continued). "In this pathway, hypertrophy stimulation will increase plasma calcium levels and activate can dephosphorylate NFAT3, after which the dephosphorylated NFAT3 enters the nucleus and interacts with GATA4 to activate multiple genes related to myocardial hypertrophy." (PMID 36177479, 2022). "Furthermore, the knockdown of Ankrd1 attenuated phenylephrine-induced cardiac hypertrophy by inhibiting ANKRD1/ERK/GATA4 (involved in regulating cardiomyocyte growth) complex formation in the sarcomere and its nuclear translocation." (PMID 36551326, 2022). "Furthermore, it also suppressed the expression of fibrosis markers COL1A1, CTGF, and uPA and downregulated cardiac-hypertrophy-associated markers such as calcineurin, NFATC3, GATA4, pGATA4 and BNP." (PMID 35890118, 2022). "In addition, cardiac hypertrophy-related GATA4-dependent genes expression, including Nppa and Myh7, also enhance the reaction to the adverse stimulation." (PMID 35958418, 2022). "P300 overexpression in mouse cardiomyocytes stimulates the expression of the GATA4-dependent genes related to cardiac hypertrophy, including natriuretic peptide precursor A(Nppa, mediating the translation of ANP), prepro-endothelin-1(ET-1), and β-myosin heavy chain (Myh7)." (PMID 35958418, 2022). "For example, overexpression of GATA4 can lead to cardiac hypertrophy and heart failure." (PMID 36177479, 2022). "Interestingly, in utero PM2.5 exposed adult mice developed cardiac hypertrophy, and that is associated with increased expression of p300/CBP and increased acetylation of histone H3K9 and expression of GATA4 and Mef2e cardiac transcription factors." (PMID 34831061, 2021). "GATA factors play important roles in heart development and cardiac diseases, and overexpression of Gata4 or Gata6 in mouse hearts could lead to cardiac hypertrophy." (PMID 34003819, 2021). "It is unclear what the role(s) of Gata4 in miR-208a-induced cardiac hypertrophy is." (PMID 34957257, 2021). "For instance, circRNA_000203 exacerbates cardiac hypertrophy via the miR-26b-5p/Gata4 axis." (PMID 34488538, 2021). "Overexpressed RACK1 interacts with GATA4 and disrupts PE-induced p300-GATA4 activation complex formation on hypertrophic genes and thus suppresses hypertrophy in neonatal rat cardiomyocytes and cardiac hypertrophy in salt-sensitive Dahl (DS) rat model of hypertension." (PMID 34831061, 2021). "Indeed, inhibition of PRMT5 facilitates cardiac hypertrophy through suppression of p300-mediated transcriptional activation of GATA4." (PMID 33424610, 2020). "Thus, the pathway of calcineurin/NFAT/GATA4 acts as an essential effector during cardiac hypertrophy formation." (PMID 33374365, 2020). "Therefore, the results indicate that BA treatment inhibited DOX-induced cardiac hypertrophy through blocking of GATA-4 activation, the transcriptional regulator for the generation of cardiac hypertrophy." (PMID 33374365, 2020). "Additionally, these results are in line with previous reports that PRMT5 protected against cardiac hypertrophy by methylating GATA4 to hamper p300-mediacted GATA acetylation, and by symmetric di-methylating Histone H4R3 via regulation of Filip1L/β-catenin." (PMID 33424610, 2020). "In the development of cardiac hypertrophy, GATA4 plays a role by targeting genes of pressure overload associated proteins, such as angiotensin II type 1a receptor, myosin heavy and light chains, troponins, brain natriuretic peptide (BNP), atrial natriuretic peptide (ANP) and many more." (PMID 31717562, 2019). "Notably, GATA4 is remarkably activated in mice of Kindlin-2 knockout mice, providing a precise explanation as to Kindlin-2 regulates cardiac hypertrophy." (PMID 31767831, 2019). "Importantly, this finding was confirmed by EMSA assay, which shows that GRK5-NT significantly reduces both NFAT and GATA-4 ability to bind DNA in an established model of cardiac hypertrophy (i.e., SHR)." (PMID 29543709, 2018).